HDAC1 (histone deacetylase 1)
Diseases named in the same sentence as HDAC1 in open-access papers (continued):
Sharing a sentence is not in itself a finding about the gene and the disease.
proteinopathies (1 paper, 2020). "Collectively, these findings outline a pathway in TDP‐43 proteinopathies by which HDAC1 deregulation causes dysfunctional transcriptional repression of cell cycle‐related genes and an increased susceptibility to DNA damage." (PMID 32449313, 2020). "However, the pathological mechanisms of FTLD‐TDP underlying TDP‐43 proteinopathies are unclear, and the role of HDAC1 is also poorly understood." (PMID 32449313, 2020). "To clarify the pathogenic role of HDAC1 deregulation in FTLD‐TDP Tg mice, we examined the association between HDAC1 mislocalization and TDP‐43 proteinopathies in the progression of FTLD‐TDP." (PMID 32449313, 2020). "Together, these results confirm the strong association between HDAC1 function loss and TDP‐43 proteinopathies in the pathogenesis of FTLD‐TDP." (PMID 32449313, 2020). "Having confirmed the involvement of cell cycle aberrance and DNA damage in neuronal degeneration in FTLD‐TDP Tg mice, we further sought to investigate the role of HDAC1 in the pathogenesis of TDP‐43 proteinopathies." (PMID 32449313, 2020). "These suggest a pathogenic feature for HDAC1 function loss in aberrant cell cycle activity and DNA damage and indicate that recovery of nuclear HDAC1 activity is sufficient to restore the pathogenesis of TDP‐43 proteinopathies." (PMID 32449313, 2020). "TDP‐43 proteinopathies may play an essential role in the reduced nuclear levels and activity of HDAC1, and this deregulation may induce aberrant cell cycle activity and DNA damage during disease progression in FTLD‐TDP." (PMID 32449313, 2020). "Together, our findings illuminate the role of HDAC1 in TDP‐43 proteinopathies and further support the hypothesis that restoring HDAC1 activity may be a feasible approach to treating FTLD‐TDP and ALS." (PMID 32449313, 2020). "Moreover, TDP‐43 proteinopathies may also influence HDAC1 activity due to the interference of the Zn‐dependent catalytic domain, such that HDAC1's functional domain is blocked." (PMID 32449313, 2020). "Theophylline also restored nuclear HDAC1 activity in the FTLD‐TDP Tg mice (Fig EV2C), which implies that improving nuclear HDAC1 function, is potential for reversing TDP‐43 proteinopathies in these mice." (PMID 32449313, 2020). "Here, our findings indicate that HDAC1‐TDP‐43 interactions result in the export of nuclear HDAC1, which may in turn promote TDP‐43 acetylation and aggravate TDP‐43 proteinopathies." (PMID 32449313, 2020). "However, at the age of 6 months, when the impairments of the Tg mice become more pronounced, we observed obvious co‐mislocalization of TDP‐43 and HDAC1 from the nucleus to the cytosol, which corresponded to the pathogenesis of TDP‐43 proteinopathies." (PMID 32449313, 2020). "Therefore, it is more convincing that only HDAC1, but not HDAC2, is affected by nuclear TDP‐43 mislocalization, thus contributes to TDP‐43 proteinopathies." (PMID 32449313, 2020).
pulmonary emphysema (1 paper, 2021). A subcategory of chronic obstructive pulmonary disease (COPD). "Levels of histone deacetylase 1 (HDAC1) and sirtuin 1 (SIRT1), which are reported to participate in the mechanisms for experimental pulmonary emphysema, were significantly diminished in the lungs of the triple n/i/eNOSs−/− mice." (PMID 34764368, 2021). "Thus, it is likely that decreased HDAC1 and SIRT1 levels were also involved in the development of spontaneous pulmonary emphysema in the triple n/i/eNOSs−/− mice." (PMID 34764368, 2021).
restrictive cardiomyopathy (1 paper, 2025). A type of heart disorder referring to the inability of the ventricles to fill with blood because the myocardium (heart muscle) stiffens and looses its flexibility. "Although HDAC2 is activated by stress signals (such as HSP70 and CK2α1) and promotes hypertrophic gene expression, HDAC1 is associated with restrictive cardiomyopathy and mitochondrial dysfunction." (PMID 40660005, 2025). "The mutant cardiac troponin I (cTnIR193H) interacts with HDAC1, reducing PDE4D levels in cardiomyocytes through promoter degradation, which contributes to the development of restrictive cardiomyopathy." (PMID 40660005, 2025).
retinal ischemia (1 paper, 2019). A ischemic disease that involves the retina. "Among the various HDAC isoforms, previous studies have demonstrated that HDAC1, 2, 3, and 6 are the major contributors to total HDAC activity in rodent retina and, importantly, the increased retinal HDAC activity induced by retinal ischemia may mostly attributed to increased HDAC1 and 2 activity." (PMID 31627491, 2019).
rhabdoid tumor (1 paper, 2013). An aggressive malignant embryonal neoplasm usually occurring during childhood. "Here we demonstrate that several HDACs, including HDAC1 and 2, are overexpressed in primary rhabdoid tumors and tumor cell lines." (PMID 23764045, 2013). "Comparing protein expression in different SMARCB1 negative rhabdoid tumor cell lines (A204, G401, BT16, BT12) with ESCs (OG2; as a control with known highly expressed HDAC1 and HDAC2) demonstrate that group 1 HDAC levels are similarly expressed in rhabdoid tumors and ESC." (PMID 23764045, 2013). "HDAC1 and HDAC2 are overexpressed in primary rhabdoid tumors and rhabdoid tumor cell lines." (PMID 23764045, 2013).
scleroderma (1 paper, 2013). Scleroderma is a rare autoimmune connective tissue disorder characterized by abnormal hardening of the skin and, sometimes, other organs. "Our study demonstrates that specific inhibition of HDAC1 has a pro-fibrotic effect, also in scleroderma fibroblasts (data not shown)." (PMID 24058639, 2013).
scrapie (1 paper, 2023). A fatal disease of the nervous system in sheep and goats, characterized by pruritus, debility, and locomotor incoordination. "A downregulation of HDAC1 expression was also observed in clinical scrapie sheep compared to controls (p = 0.1), in contrast with the increased expression displayed by the clinical Tg338 mice." (PMID 36675131, 2023).
small cell lung carcinoma (1 paper, 2022). Small cell lung cancer (SCLC) is a highly aggressive malignant neoplasm, accounting for 10-15% of lung cancer cases, characterized byrapid growth, and early metastasis. "Recent in-vitro and animal model work in small cell lung cancer has demonstrated that CREBBP mutant tumors may be preferentially sensitive to HDAC1 inhibitors." (PMID 36514795, 2022).
Splenomegaly (1 paper, 2016). Abnormal increased size of the spleen. "To determine how the lack of Hdac1 and Hdac2 in B cells impacts Eμ-myc tumorigenesis, we analysed 8-week old mice by first measuring spleen weight, since Eμ-myc mice typically have splenomegaly." (PMID 27886239, 2016).
sterility (1 paper, 2022). "The present results suggest that the decreased level of HAT1 and increased level of HDAC1 may result in the decreased H3K9 acetylation in cattle-yaks and might be associated with their sterility." (PMID 36009610, 2022).
T-cell leukemia (1 paper, 2013). A malignant disease of the T-lymphocytes in the bone marrow, thymus, and/or blood. "For example, in an adult T cell leukemia patient, the 5′ region of the BCL11B gene was found fused to intron 3 of the HELIOS gene, which interestingly, we also identified as HDAC1 interaction." (PMID 23752268, 2013).
thymic epithelial tumors (1 paper, 2023). "In this study we attempt the first comprehensive evaluation of six class I (HDAC1, HDAC2, HDAC3) and II HDACs (HDAC4, HDAC5, HDAC6) expression patterns in thymic epithelial tumors (TETs), with the aim of identifying their possible association with a number of clinicopathological parameters." (PMID 36901692, 2023).
thymic tumors (1 paper, 2025). "Notably, T cell-specific deletion of Hdac1 in non-ALK-transgenic mice also induced thymic tumors in approximately a quarter of mice at older ages, whereas no signs of malignant transformation were observed in thymi of mice with a deletion of Hdac2." (PMID 40175628, 2025).
tongue cancer (1 paper, 2021). A malignant neoplasm affecting the tongue.
type 1 diabetic (1 paper, 2025). "Notably, in vivo experiments using AD-1 in streptozotocin-induced type 1 diabetic mice confirmed its therapeutic efficacy, significantly downregulating key diabetic markers (e.g., NFKB1 and HDAC1) in pancreatic tissues—a finding unreported in prior studies." (PMID 40508108, 2025).
uveal melanoma (1 paper, 2021). A melanoma derived from melanocytes of the uveal tract. "The aim of this study is to assess the clinical significance and prognostic role of the of HDAC-1, -2, -4, and -6 immunohistochemical expression, in 75 uveal melanoma (UM) cases." (PMID 34638249, 2021).
cancer (439 papers, 2005 to 2026). A tumor composed of atypical neoplastic, often pleomorphic cells that invade other tissues. "Ortho-aminoanilides, for instance, demonstrate preferential inhibition of class I HDACs, particularly HDAC1, 2, and 3, which are closely linked to cancer progression." (PMID 40284012, 2025). "Here we elucidate the mechanism by which hotspot cancer mutations in the E3 ligase KBTBD4 can reprogramme its PPIs to promote aberrant degradation of HDAC1/2 corepressor complexes in MB, establishing HDAC1/2 as the target of mutant KBTBD4." (PMID 39939763, 2025). "Further experimental studies, including in vitro and in vivo evaluations, are essential to confirm the efficacy and safety of Alectinib in HDAC1-associated cancer therapeutics." (PMID 39752394, 2025). "HDAC1, 2, and 3 impact the transcription of genes associated with proliferation and apoptosis of cancer cells, increasing cancer cell proliferation and preventing apoptosis." (PMID 40283998, 2025). "The overexpression or dysregulation of HDAC1 is observed in many cancers, including HCC, and is associated with its prognosis." (PMID 39199296, 2024). "While class I HDAC family members (HDAC1/2/3/8) were positively associated with cancer stemness across most of the tested tumor types, class IIA HDAC members (HDAC4/5/7/9) exhibited an inverse correlation." (PMID 39063083, 2024). "HDAC1 is involved in various cellular functions, and its dysregulation has been implicated in cancer development and progression." (PMID 37888480, 2023). "Overexpression of HDAC1 can cause abnormal cell cycle regulator E2F transcription factor, which leads to the production of cancer cells." (PMID 36644230, 2023). "That SnoN associates in a sumoylation-dependent manner with HDAC1 and p300 raised the question of the functional consequences of this interaction in cancer cells." (PMID 37414747, 2023). "The level of HDAC1 expression can also serve as a good diagnostic and prognostic marker of malignant neoplasms of the gastrointestinal tract, especially in colorectal carcinoma." (PMID 37834214, 2023). "As the research progresses, HDAC1 has also been demonstrated to be apparently upregulated in a variety of cancers and the loss of HDAC1 interdicts tumor progression and induces apoptosis." (PMID 37760477, 2023). "Despite being largely overlooked in previous research, GSE1 caught our attention due to its robust interaction with HDAC1 and its previous association with cancer." (PMID 37878419, 2023). "In contrast, HDAC1 knockdown causes cell cycle arrest, reduces cancer cell viability, and induces cancer cell apoptosis." (PMID 35053925, 2022). "High expression of HDAC1 is significantly associated with elevated cancer-specific mortality in LIHC." (PMID 35733217, 2022). "In particular, the HDAC1 isoform has been associated with various types of cancer and its overexpression in gastric and prostate cancers has been reported." (PMID 36267272, 2022). "Meanwhile, HDAC1 is strongly associated with higher stage cancer, lymph node metastasis, and vascular invasion, and its overexpression indicates poor prognosis in patients with intrahepatic CC." (PMID 35395834, 2022). "Whereas TET2 global deacetylation mediated by histone deacetylases, 1 and 2 (HDAC1 and 2) leads to reduced enzymatic activity triggering the emergence of abnormal DNA methylation profiles typically associated with cancer." (PMID 35159097, 2022). "Up-regulation of HDAC1 has been shown to be associated with adverse prognosis of various cancers, and plays critical roles in cellular senescence, aging, myelination, and adult neurogenesis." (PMID 34667186, 2021).
cancer (continued). "The mechanisms underlying HDAC1-driven cancer development involve in several cellular processes, including cell cycle, apoptosis, DNA-damage response, and autophagy." (PMID 33482915, 2021). "This work reveals a novel underlying mechanism, SOX4-HDAC1 axis, for stemness maintenance of human cancer and suggests that HDAC1 inhibition should be an effective precision therapeutic strategy for eradicating SOX4-drived human CSCs." (PMID 33482915, 2021). "Due to the close involvement of HDAC1 in regulating cell fate, abnormal expression and activity of HDAC1 have been implicated in cancers." (PMID 33976119, 2021). "This fact causes HDAC1 inhibition, in combination with antigen-specific adoptive T cell therapy, to overtake immune refractory cancers, leading to immune-mediated tumor regression." (PMID 32455616, 2020). "In the outlier control samples, we identified proteins DNMT1 (DNA Methyltransferase 1), INSR (insulin receptor) and HDAC1 (histone deacetylase 1) displaying a regulation pattern previously associated with different cancer types, including MIBC." (PMID 30419021, 2018). "HDAC1 has been reported to be closely associated with several types of cancer, but the precise role of HDAC1 in gastrointestinal cancer is not clear." (PMID 28424407, 2017). "Disruption of HDAC1 function has been associated with many disorders including cancer and neuro-degenerative diseases including Alzheimer's disease." (PMID 27852975, 2016). "Different human cancer cell lines depleted of HDAC1 have an aberrant cell cycle, accompanied by loss of mitotic cells and an increase in apoptosis." (PMID 27458029, 2016). "Several studies point to overexpression of class I HDACs, in particular HDAC1, as a cancer marker associated with a poor prognosis." (PMID 25613585, 2015). "Class I HDACs are divided into four isoforms (HDAC-1, -2, -3 and -8) and are known to be associated with an overexpression in different types of cancer such as colon and prostate cancer." (PMID 24624923, 2014). "Nonetheless, the ultimate loss of maspin expression in high grade carcinoma will contribute to yet an additional increase of HDAC1 activity, on top of the increased HDAC1 expression, thus promoting tumor progression." (PMID 24278104, 2013). "Normal epithelial tissue, benign tumor or better differentiated carcinoma with better prognosis and better overall patient survival are associated with nuclear maspin that has a stronger affinity towards HDAC1 than factor X." (PMID 24278104, 2013). "The accumulating evidences suggest that HDAC1 overexpression appears especially common in cancers of the gastrointestinal system and is associated with dedifferentiation, enhanced proliferation, invasion, advanced disease and poor prognosis." (PMID 22496786, 2012). "Consistently, increasing evidence suggested the aberrant expression of HDAC1 in neoplastic diseases, and demonstrated that HDAC1 depletion causes growth arrest and apoptosis of certain human cancer cells." (PMID 22496786, 2012). "Although it is unclear which of the eleven HDAC proteins is involved in cancer formation, the activity of HDAC1 has been linked to cell proliferation, a hallmark of cancer." (PMID 17022812, 2006). "Similarly, HDAC1’s positive association suggests a potential role in antitumor immunity, despite its known immunosuppressive functions in breast and other cancers." (PMID 40430573, 2025). "While all four classes of HDACs have been implicated in various cancers, Class I HDACs (HDAC1, HDAC2, HDAC3, and HDAC8) are generally considered the most directly and frequently associated with tumorigenesis and are often the primary targets in initial cancer therapeutic strategies." (PMID 41440016, 2025).